RNVU1-8 (RNA, variant U1 small nuclear 8)
Synonyms: vU1.8; RNU1-145
Gene: Small nuclear RNA gene on chromosome 1 (147,084,616 to 147,084,756, reverse strand). Ensembl gene ENSG00000286172.
Gene Ontology:
Molecular function: pre-mRNA 5'-splice site binding
Biological process: mRNA 5'-splice site recognition
Cellular component: U1 snRNP